YBX1 (Y-box binding protein 1)
Diseases named in the same sentence as YBX1 in open-access papers (continued):
Sharing a sentence is not in itself a finding about the gene and the disease.
pulmonary fibrosis (3 papers, 2023 to 2025). Chronic progressive interstitial lung disorder characterized by the replacement of the lung tissue by connective tissue, leading to progressive dyspnea, respiratory failure, or right heart failure. "Loss of YBX1 compromises these protective mechanisms, leading to increased epithelial apoptosis and impaired repair capacity, both of which are central to the progression of pulmonary fibrosis." (PMID 41254784, 2025). "Therapeutic targeting of YBX1 remains a largely unexplored area in idiopathic pulmonary fibrosis (IPF)." (PMID 41254784, 2025). "This study systematically investigates the potential role of YBX1 in the pathogenesis of idiopathic pulmonary fibrosis (IPF) through multi-omics data integration, machine learning modeling, and molecular simulations." (PMID 41254784, 2025). "Nevertheless, rigorous in vitro and in vivo validation will be required to confirm its efficacy and clarify the extent to which it directly modulates YBX1 activity in pulmonary fibrosis." (PMID 41254784, 2025). "These analyses aimed to elucidate the role of YBX1 in the functional differentiation of AT2 cells, particularly within the pathophysiological context of pulmonary fibrosis." (PMID 41254784, 2025).
systemic lupus erythematosus (3 papers, 2024 to 2025). An autoimmune multi-organ disease typically associated with vasculopathy and autoantibody production. "The expression of YBX1 was significantly lower in apoptotic T cells and activated T cells from Systemic Lupus Erythematosus (SLE) patients compared to nonapoptotic T cells and activated T cells from healthy individuals." (PMID 38255791, 2024).
thyroid cancer (3 papers, 2020 to 2025). "We then used immunohistochemical analysis to evaluate the expression levels of SOX12, YBX1 and LDHA in thyroid cancer tissues with different expression levels of SOX12." (PMID 40593465, 2025). "Nevertheless, YBXs might have a safeguarding function in specific categories of malignancies, like YBX1 in colon adenocarcinoma (COAD) and thyroid carcinoma (THCA), and YBX2 in stomach adenocarcinoma (STAD)." (PMID 38698857, 2024).
acute lymphoblastic leukemia (2 papers, 2024 to 2025). Leukemia with an acute onset, characterized by the presence of lymphoblasts in the bone marrow and the peripheral blood. "Lastly, in T-cell acute lymphoblastic leukemia (T-ALL), downregulation of YBX1 results in inhibition of total AKT, p-AKT, total extracellular signal-regulated kinase (ERK), and p-ERK expression, playing a pivotal role in the development of T-ALL." (PMID 40799245, 2025). "YBX1, vital in cell survival for solid tumors and acute myeloid leukemia, shows heightened levels in T cell acute lymphoblastic leukemia (T-ALL)." (PMID 38255791, 2024).
autoimmune disease (2 papers, 2009 to 2024). A disorder resulting from loss of function or tissue destruction of an organ or multiple organs, arising from humoral or cellular immune responses of the individual to their own tissue constituents. "YBX1 plays a pivotal role in autoimmune disease development by modulating immune cell activation and the expression of immune molecules." (PMID 39727969, 2024). "Beyond cancer, YBX1 also plays a critical role in autoimmune diseases, senescence-related disorders, and inflammatory processes." (PMID 39727969, 2024). "Although current studies have established YBX1 as a regulator of immune-inflammatory responses, further research is needed to delineate its role in specific autoimmune diseases, particularly through large-scale cohort studies and mechanistic experiments." (PMID 39727969, 2024). "Additionally, YBX1 nuclear translocation can exacerbate other autoimmune diseases, like SLE, by upregulating Multidrug Resistance Protein 1 (MDR1) transcription and increasing membrane P-glycoprotein (p-gp) expression." (PMID 39727969, 2024). "YBX1 is crucial in regulating the immune system and preventing autoimmune diseases." (PMID 39727969, 2024). "Additionally, YBX1 can modulate the progression of autoimmune diseases such as SLE and type 1 diabetes by affecting signal pathway activation and the production of autoantigens and autoantibodies." (PMID 39727969, 2024). "YBX1 acts as an autoantigen in the P-body of serum from primary biliary cirrhosis patients, prompting autoimmune responses and autoantibody production, thus contributing to autoimmune disease development." (PMID 39727969, 2024). "In immune responses, YBX1 mainly impacts the activation and infiltration of immune cells, expression of immune molecules, antigen presentation, and immune-related signaling pathways, playing a regulatory role in autoimmune diseases, tumor immunity, and immunotherapy." (PMID 39727969, 2024). "Antigens YBX1, HMG-14, and CENPB which showed also informative AUC values are involved in the autoimmune disease systemic sclerosis." (PMID 19284601, 2009).
bone cancer (2 papers, 2008 to 2025). A primary or metastatic malignant neoplasm affecting the bone or articular cartilage. "In bone cancer, YBX1 stabilizes pro-metastatic mRNA by recognizing sequence motifs shared by the 3’ end of tRNA fragments(tRF)-GlyTCC and RUNX2, thereby inhibiting tumor metastasis in primary bone cancer progression." (PMID 40799245, 2025).
colon adenocarcinoma (2 papers, 2023 to 2024). "Moreover, YBX1 could induce oxaliplatin resistance in colon adenocarcinoma cell lines by induction of NONO and RALY proteins." (PMID 35861369, 2023).
cutaneous melanoma (2 papers, 2021 to 2022). A primary melanoma arising from atypical melanocytes in the skin. "Several m5C-regulators are associated with overall survival prognosis in cutaneous melanoma (DNMT2, NSUN1, NSUN3, NSUN6 and YBX1)." (PMID 36060802, 2022).
heart failure (2 papers, 2023). Inability of the heart to pump blood at an adequate rate to meet tissue metabolic requirements. "However, it is unclear whether those findings are relevant to human hearts, but Ybx1 expression is decreased in human heart failure data sets, suggesting that Ybx1 expression is dysregulated in human hearts as well." (PMID 37378715, 2023).
Intellectual disability (2 papers, 2024 to 2025). "We focused on YBX1 and YBX3 because they are expressed in the adult nervous system and found that several large CNVs involving either the YBX1 or YBX3 loci, as well as one rare missense YBX3 variant, are present in individuals with neurological symptoms including intellectual disability." (PMID 39423228, 2024). "The most common symptom reported in individuals with CNV deletions including the YBXs is intellectual disability, as 37.5% of individuals with CNV deletions containing YBX1 and 80% of individuals with CNV deletions in YBX3 have intellectual disability." (PMID 39423228, 2024).
ischaemia (2 papers, 2017 to 2025). "In addition, endothelial Carm1 upregulates VEGF through Y-box-binding protein-1 (YB1), promoting angiogenesis and functional blood-flow recovery in ischemia models." (PMID 40918432, 2025).
lung squamous cell carcinoma (2 papers, 2023 to 2025). "THOC3 interaction with YBX1 modifies PFKFB4 mRNA, promoting the progression of lung squamous cell carcinoma." (PMID 40799245, 2025). "In lung squamous cell carcinoma, gasdermin E (GSDME) interacts with YBX1, facilitating its transport to the nucleus, where it directly promotes mucin expression." (PMID 40799245, 2025).
myelofibrosis (2 papers, 2020 to 2022). A partial or complete replacement of the bone marrow stroma by fibrous tissue. "The expression of YBX1 was determined to be elevated in bone marrow from MPN patients (PV, ET, and myelofibrosis) compared to healthy bone marrow cells, suggesting cells from some MPN patients may be more sensitive to a strategy to target YBX1 function." (PMID 35082276, 2022).
myeloproliferative neoplasm (2 papers, 2022 to 2025). A clonal hematopoietic stem cell disorder, characterized by proliferation in the bone marrow of one or more of the myeloid (i.e., granulocytic, erythroid, megakaryocytic, and mast cell) lineages. "Recently, our group reported on a novel role of YBX1 in JAK2-mutated myeloproliferative neoplasms (MPN)." (PMID 34465866, 2022). "Recently, our group identified YBX1 as a mediator of disease persistence in JAK2-mutated myeloproliferative neoplasms." (PMID 34465866, 2022). "In myeloproliferative neoplasms (MPN), YBX1 contributes to disease persistence, making it a therapeutic target in both AML and MPN." (PMID 40374809, 2025).
oral squamous cell carcinoma (2 papers, 2022 to 2024). "YBX1 was reported to promote IL-4 expression in oral squamous cell carcinoma cells." (PMID 38575607, 2024). "In addition, YBX1 promoted IL-4 expression in oral squamous cell carcinoma cells." (PMID 38575607, 2024).
oral submucous fibrosis (2 papers, 2020 to 2025). "YBX1 promotes the expression of α-SMA and p-Smad2 along with the progression of human buccal mucosal fibroblasts to myofibroblasts transition in oral submucous fibrosis, which correlates with TGF-β signaling pathway." (PMID 40346063, 2025).
osteoarthritis (2 papers, 2024 to 2025). A noninflammatory degenerative joint disease occurring chiefly in older persons, characterized by degeneration of the articular cartilage, hypertrophy of bone at the margins and changes in the synovial membrane. "By triggering the PI3K/Akt/mTOR singling pathway through the transcription factor YBX1 (Y-Box binding protein 1), KLF3-AS1 slows the advancement of osteoarthritis." (PMID 39273098, 2024).
Peritoneal Fibrosis (2 papers, 2022 to 2024). Disorder characterized by a wide range of structural changes in PERITONEUM, resulting from fibrogenic or inflammatory processes. "It has been already known that the proliferation of peritoneal mesothelial cells could be affected by the Y-box-binding protein 1 (YBX1) and Twist1 proteins during the development of peritoneal fibrosis caused by high glucose." (PMID 35380292, 2022).
Rett syndrome (2 papers, 2021 to 2023). A severe neurodevelopmental disorder affecting the central nervous system.
rhabdomyosarcoma (2 papers, 2023 to 2025). A rare aggressive malignant mesenchymal neoplasm arising from skeletal muscle. "In rhabdomyosarcoma, MYC and YBX1 regulate each other; MYC binds to the YBX1 promoter, and YBX1 binds to MYC mRNA, forming a MYC-YBX1 circuit that maintains stem cell-like vincristine-resistant cells." (PMID 40799245, 2025).
squamous cell carcinoma (2 papers, 2022 to 2023). A carcinoma arising from squamous epithelial cells. "Specifically, YBX1 binds to a long noncoding RNA in squamous cell carcinoma to facilitate tumor cell growth and metastasis." (PMID 37345125, 2023).
steatosis (2 papers, 2025). Increased lipid within the cytoplasm of cells. "In an in vitro model of steatosis, induced by treating the immortalized mouse hepatocyte cell line AML12 with palmitic acid, YBX1 expression was consistently upregulated." (PMID 40959287, 2025). "The expression level of CD36 was positively correlated with that of YBX1 in the liver tissues of MASLD patients and in an in vitro steatosis model." (PMID 40083711, 2025). "Moreover, although not observed in basal conditions, a YBX1/CD36 positive feedback loop was observed in the in vitro model of steatosis, suggesting that lipid accumulation in MASLD may be a self-promoting process." (PMID 40959287, 2025).
ZIKV infection (2 papers, 2019 to 2024). "Zika virus (ZIKV) infection does not significantly impact the association of IGF2BP2 with IGF2BP1, IGF2BP3, and YBX1." (PMID 39565347, 2024).
atrial fibrillation (1 paper, 2025). A disorder characterized by an electrocardiographic finding of a supraventricular arrhythmia characterized by the replacement of consistent P waves by rapid oscillations or fibrillatory waves that vary in size, shape and timing and are accompanied by an irregular ventricular response. "Interestingly, in non-tumor contexts such as atrial fibrillation (AF) and sleep deprivation (SD), machine learning approaches identified YBX1 as a key diagnostic gene." (PMID 41346602, 2025).
cardiac ischemia (1 paper, 2025).
chondrosarcoma (1 paper, 2023). A malignant cartilaginous matrix-producing mesenchymal neoplasm arising from the bone and soft tissue. "In the current study, we suggested a possible regulatory effect on MMP13 mRNA by MIA/CD-RAP via YBX1 in differentiated chondrocytes and SW1353 chondrosarcoma cells." (PMID 36672165, 2023).
hemorrhage (1 paper, 2023). Loss of blood from the vascular compartment to the exterior or into nonvascular body space as a result of rupture or severance of the blood vessels. "To shed light on this issue, we investigated erythropoietin (Epo), erythropoietin receptor (EpoR), and Y-box binding protein 1 (YB-1) concentrations in the fracture zone in a porcine MT + traumatic hemorrhage (TH) model." (PMID 36639666, 2023).
infertile (1 paper, 2021). "The downregulation of ACO2 and AK1 and the upregulation of YBX1 in sperm from infertile males with severe oligoasthenoteratozoospermia requiring ICSI treatment were identified and compared." (PMID 34213690, 2021). "Moreover, we experimentally validated the downregulation of ACO2 and AK1 and the upregulation of YBX1 in sperm from infertile men." (PMID 34213690, 2021). "Third, the differentially expressed proteins that were validated, namely AK1, ACO2, and YBX1, were not subjected to further in-depth investigation; thus, their roles and mechanisms concerning infertility remain unconfirmed." (PMID 34213690, 2021). "Therefore, we postulate that the upregulation of YBX1 contributes to the downregulation of AK1, abnormal energy metabolism pathways, and subsequent infertility, although a more detailed mechanistic study is required." (PMID 34213690, 2021).
injury (1 paper, 2019). Damage inflicted on the body as the direct or indirect result of an external force, with or without disruption of structural continuity. "Considering our finding that circAnks1a siRNA completely inhibited the upregulation of VEGFB protein induced by nerve injury, another YBX1-independent pathway might exist through which circAnks1a regulates the expression of VEGFB in the setting of nerve injury." (PMID 31511520, 2019). "Taken together, our findings indicated that circAnks1a facilitated the nuclear translocation and promoter binding of YBX1, thereby inducing VEGFB upregulation and neuropathic pain induced by nerve injury." (PMID 31511520, 2019). "Taken together, the present study for the first time demonstrated that enhanced interaction between circAnks1a and YBX1 can facilitate YBX1 nuclear translocation and its binding to the Vegfb promoter region and thereby lead to VEGFB upregulation induced by nerve injury." (PMID 31511520, 2019).
liver steatosis (1 paper, 2025). "Collectively, these data indicate that YBX1 deficiency reduces lipid accumulation in hepatocytes and mitigates liver steatosis in MASLD mice." (PMID 40083711, 2025). "The up-regulation of CD36 attenuated the reduction of hepatic steatosis mediated by hepatic YBX1 deficiency in MASLD mouse models." (PMID 40083711, 2025). "In contrast, our study initially validated the increased expression of YBX1 under fatty liver conditions using clinical samples and clinical databases." (PMID 40083711, 2025). "Bioinformatics approaches were utilized to explore the relationship between YBX1 expression and hepatic steatosis, and to identify potential downstream genes." (PMID 40083711, 2025). "Furthermore, our results indicated that the expression of YBX1 is positively correlated with the severity of hepatic steatosis." (PMID 40083711, 2025). "In addition, the hepatocyte-specific knockout of YBX1 reduced lipid accumulation and improved liver steatosis in the MASLD mouse model, implying that YBX1 is involved in the progression of MASLD." (PMID 40083711, 2025). "This study reveals a novel mechanism of liver steatosis and shows that targeting YBX1 may represent a potential approach for MASLD treatment." (PMID 40083711, 2025). "Notably, targeting YBX1 in hepatocytes alleviates lipid accumulation and hepatic steatosis." (PMID 40083711, 2025). "This study showed that YBX1 is up-regulated in MASLD and positively correlated with the severity of hepatic steatosis." (PMID 40083711, 2025). "Hence, we can conclude that YBX1 enhances hepatic lipid uptake by positively regulating the transcription of CD36 and exerts a pivotal role in liver steatosis." (PMID 40083711, 2025).
malignant glioma (1 paper, 2024). A grade III or grade IV glioma arising from the central nervous system. "The presence of the facilitation of 2Ig expression by YBX1 and the following positive correlation with high‐malignant glioma in this study is consistent with previously studies that high expression of YBX1 appears to the carcinogenic effect." (PMID 39048916, 2024).
metastasis (1 paper, 2026). The spread or migration of cancer cells from one part of the body (where they first appeared) to another. "A study that analyzed tissue microarrays from 11,152 PCas showed that YBX1 was detectable in 86.3% of PCa, absent or weak relative to normal epithelium, and that YBX1 nuclear staining was strongly associated with poor patient prognosis, tumor stage, Gleason score, and lymph node metastasis." (PMID 41507135, 2026).
metastatic colorectal cancer (1 paper, 2021). "In this study, we demonstrate that chemotherapeutic agent FOLFOX, commonly used for drug-resistant/metastatic colorectal cancer (CRC) treatment, induces overexpression of CD44v6, MDR1, and oncogenic transcription/translation factor Y-box-binding protein-1 (YB-1)." (PMID 33451103, 2021).
Osteopenia (1 paper, 2025). Osteopenia is a term to define bone density that is not normal but also not as low as osteoporosis. "Importantly, YBX1 knockout has been proven to cause osteopenia, while its function in SMA-related endochondral ossification defects remains unclear." (PMID 41320719, 2025).
postmenopausal osteoporosis (1 paper, 2024). Metabolic disorder associated with fractures of the femoral neck, vertebrae, and distal forearm. "Notably, our results demonstrated Ybx1 expression was slightly reduced, which correlates with the postmenopausal osteoporosis-related loss of type H vessels and bone mass." (PMID 38385749, 2024).
pulmonary hypertension (1 paper, 2026). Increased pressure within the pulmonary circulation due to lung or heart disorder. "Nuclear YBX1 acts as a transcription factor, directly activating HIF‐1α transcription in pathological pulmonary hypertension." (PMID 41482854, 2026).
retinoblastoma (1 paper, 2025). A malignant tumor that originates in the nuclear layer of the retina. "Mechanistically, NSUN2 and YBX1 promoted the malignant behavior and in vitro glycolysis of retinoblastoma through HKDC1, and accelerated tumor growth in vivo." (PMID 41462962, 2025). "In retinoblastoma studies, NSUN2 and YBX1 mediated the m5C modification and mRNA stability of HKDC1, where the global and mRNA m5C levels of retinoblastoma were significantly higher than those of normal retina." (PMID 41462962, 2025).
sarcomatoid carcinoma (1 paper, 2025). A malignant epithelial neoplasm characterized by the presence of spindle cells and anaplastic morphologic features. "Y-box binding protein 1 (YB-1) is a conserved protein that induces epithelial-to-mesenchymal transition and further metastasis by binding to HIF-1α and triggering the translation of HIF1A messages, enhancing metastatic capacity in sarcomatoid carcinoma." (PMID 40231252, 2025).